SF3B1 (splicing factor 3b subunit 1)
Diseases named in the same sentence as SF3B1 in open-access papers (continued):
Sharing a sentence is not in itself a finding about the gene and the disease.
myelodysplastic syndrome (continued). "Mutations in the SF3B1 splicing factor are commonly seen in myelodysplastic syndromes (MDS) and acute myeloid leukemia (AML), yet the specific oncogenic pathways activated by mis-splicing have not been fully elucidated." (PMID 36040792, 2022). "Mutations in SF3B1 are common in different hematological malignancies, and they were mostly found in myelodysplastic syndromes (MDS) and myeloproliferative neoplasms (MPN)." (PMID 35268357, 2022). "For example, splicing factor 3b subunit 1 (SF3B1) mutations have been described in myelodysplastic syndrome (MDS), and deregulated heterogeneous nuclear ribonucleoprotein A1 (hnRNPA1) expression has occurred in solid cancers." (PMID 36230624, 2022). "Recurrent somatic mutations in SF3B1 have been reported in myelodysplastic syndrome (MDS), chronic lymphocytic leukemia (CLL), and some solid tumors including uveal melanoma, breast carcinoma, pancreas adenocarcinoma." (PMID 35039052, 2022). "SF3B1 mutations occur most commonly in myelodysplastic syndromes (MDS) and are best known for their association with ring sideroblasts (RS), which are signature phenotypes." (PMID 36671709, 2022). "Somatic mutations in SF3B1 are particularly prevalent in myelodysplastic syndromes (MDS) and CLL, as well as in other solid tumors, such as UVM, pancreatic ductal adenocarcinomas and breast cancers." (PMID 34723968, 2021). "Mutations in SF3B1 have been implicated in myelodysplastic syndromes (MDS), chronic lymphocytic leukemia (CLL), chronic myeloid leukemia (CML) and a number of late-stage cancers." (PMID 34345042, 2021). "U2AF1 and SF3B1, the core components of spliceosomes, are frequently mutated in cases of myelodysplastic syndrome (MDS) and several types of solid tumor." (PMID 33397462, 2021). "Most notably, the U2 small nuclear ribonucleoprotein (snRNP) component SF3b1 has been found to be frequently mutated in blood cancers such as myelodysplastic syndromes (MDS)." (PMID 32320410, 2020). "Indeed, it has been shown that SF3B1 mutations increased the number of transcripts with retained introns as seen in myelodysplastic syndrome or they caused production of transcripts that included a shorter copy of the exon as seen in chronic lymphocytic leukemia." (PMID 32354150, 2020). "In 2011, SF3B1 mutations were identified in hematological malignancies including myelodysplastic syndromes (MDS) and chronic lymphocytic leukemia (CLL) using next-generation sequencing." (PMID 30719229, 2019). "High‐frequency mutations of SF3B1 or SRSF2 have been described in patients with myelodysplastic syndromes (MDS), chronic myelomonocytic leukemia, and acute myeloid leukemia (AML)." (PMID 29769258, 2018). "Mutations in SF3B1 are frequently found in myelodysplastic syndromes (MDS), particularly in patients with refractory anemia with ringed sideroblasts (RARS), characterized by isolated anemia." (PMID 29433555, 2018). "Heterozygous somatic mutations affecting the spliceosome gene SF3B1 drive age-related clonal hematopoiesis, myelodysplastic syndromes (MDS) and other neoplasms." (PMID 27604819, 2017). "The sequence of the SF3b1 gene of 2087 patients with myelodysplastic syndromes (MDS) showed mutations in 20% of all of them, where the K700E mutation was the most frequently found." (PMID 27610372, 2016). "The splicing factor SF3B1 is the most frequently mutated gene in myelodysplastic syndromes (MDS), and is strongly associated with the presence of ring sideroblasts (RS)." (PMID 27211273, 2016). "The splicing factor SF3B1 is the most commonly mutated gene in the myelodysplastic syndrome (MDS), particularly in patients with refractory anemia with ring sideroblasts (RARS)." (PMID 25428262, 2015). "The presence of somatic mutations in splicing factor 3b subunit 1 (SF3B1) in patients with Myelodysplastic syndromes with ring sideroblasts (MDS-RS) highlights the importance of the RNA-splicing machinery in MDS." (PMID 25481243, 2014).
myelodysplastic syndrome (continued). "In particular, Sf3b1 mutations are prevalent in a wide range of hematologic malignancies, associated with 5% of acute myeloid leukemia cases, 10–15% of chronic lymphocytic leukemia cases, and 60–80% of the myelodysplastic syndrome subtype Refractory Anemia with Ring Sideroblasts (MDS-RARS)." (PMID 24204290, 2013). "Such mutations, including hotspots in SF3B1 and U2AF1 and loss-of-function events in FUBP1, RBM5, RBM10, and ZRSR2, are recurrent in myelodysplastic syndromes, acute myeloid leukemia, chronic myelomonocytic leukemia, and multiple solid tumors 8,42–45." (PMID 41279721, 2025). "Recurrent somatic mutations in the spliceosome genes SF3B1, SRSF2, and U2AF1 are frequently identified in patients with myeloid neoplasms, such as myelodysplastic syndromes." (PMID 40386435, 2025). "Spliceosome mutations, such as those in SF3B1, SRSF2, U2AF1, and ZRSR2, are commonly found in myeloid neoplasms like myelodysplastic syndromes (MDSs) and other MPNs." (PMID 40507313, 2025). "Mutational profiles of myelodysplastic syndromes (MDS) have established that a relatively small number of genetic aberrations, including SF3B1 and SRSF2 spliceosome mutations, lead to specific phenotypes and prognostic subgrouping." (PMID 39235452, 2024). "TET2, ASXL1, DNMT3A, and SF3B1 are all known to harbor causal leukemia variants, and somatic variants in SRSF2 have been described in myelodysplastic syndrome." (PMID 39132489, 2024). "Numerous studies have highlighted the role of SF3B1 overexpression in promoting the development of various cancers such as breast cancer, prostate cancer, and myelodysplastic syndromes." (PMID 38790189, 2024). "Characterisation of SF3B1 mutant myelodysplastic syndrome (MDS) using gene signatures from multiple biological views." (PMID 39235452, 2024). "Myelodysplastic syndrome and myeloproliferative neoplasm with ring sideroblasts (RS) and thrombocytosis are renamed MDS/MPN with SF3B1 mutation and thrombocytosis, in the presence of an SF3B1 mutation of any VAF (WHO-HAEM5) or VAF ≥ 10% (ICC)." (PMID 40949653, 2024). "Mutations in splicing factors U2AF1 and SRSF2, which are associated with myelodysplastic syndrome (MDS), have been linked to R-loops and have functional incapacitation variants in SF3B1 in a zebrafish model." (PMID 37894353, 2023). "In hematological tumors, more than half of patients with myelodysplastic syndromes (MDS) show mutations in functional components of the spliceosome, commonly in serine-rich SFs, such as SF3B1, SRSF2, and U2AF1." (PMID 36611187, 2023). "More than 80% of patients with myelodysplastic syndrome with ring sideroblasts (MDS-RS) carry mutations in the SF3B1 gene; during bone marrow transplantation, SF3B1-mutated MDS-RS HSCs differentiate into characteristic ring sideroblasts." (PMID 37299568, 2023). "In fact, mutations in U2AF1, SF3B1, and SRSF2 genes are frequently found in patients affected by myelodysplastic syndromes (MDSs), which are myeloid cancers typical of the elderly." (PMID 38132139, 2023). "Similarly, certain mutations such as SF3B1 confer improved prognosis in myelodysplastic syndrome (MDS)." (PMID 35884406, 2022). "Interestingly, it has been reported that SF3B1 is frequently mutated in many types of human cancers, including myelodysplastic syndrome (MDS), chronic lymphocytic leukemia, breast cancer, uveal melanoma, and PDAC." (PMID 33932092, 2021). "Somatic SF3B1 mutations are found in approximately 30% of patients with myelodysplastic syndrome (MDS) and as many as 80% of patients with the MDS subtype characterized by ring sideroblasts (MDS-RS)." (PMID 33801781, 2021).
myelodysplastic syndrome (continued). "In various other cancers, notably myelodysplastic syndrome (MDS; 25–30%) and uveal melanoma (UM; 10–21%), heterozygous SF3B1 mutations are also highly prevalent." (PMID 33585229, 2020). "Among these factors, SF3B1, SRSF2, and U2AF1, are most frequently mutated in patients with myelodysplastic syndrome (MDS), and also commonly occurred in clonal hematopoiesis, acute myeloid leukemia (AML), CLL, and a variety of solid tumors." (PMID 32481522, 2020). "The frequency and pattern of mutation in SF3B1 and SRSF2 RNA splicing machinery genes were found to vary among myelodysplastic syndrome (MDS) patients in different populations." (PMID 31030497, 2019). "Mutations in the HEAT domains of the core splicing factor 3 B1 (SF3B1) are common in several malignancies including myelodysplastic syndrome (MDS), chronic lymphocytic leukemia (CLL), uveal melanoma and cancers of breast, liver and pancreas." (PMID 30462273, 2019). "Our results suggest that the simultaneous targeting of RNA metabolism and splicing by 8-azaguanine represents a therapeutic opportunity for SF3B1-mutant myelodysplastic syndromes." (PMID 30804405, 2019). "In this respect, large-scale genomic studies indicate that mutations of the Hsh155/SF3B1 protein recur in hematologic malignancies (i.e., myelodysplastic syndromes (MDS), chronic lymphocytic leukemia, and chronic myelomonocytic leukemia, and less commonly in solid tumors)." (PMID 31640290, 2019). "Altered or loss of function of splicing factors such as U2AF1, hnRNPA1, SF3B1, and SRSF2 results in profound deficiencies in hematopoiesis and myelodysplastic syndromes." (PMID 29875770, 2018). "Mouse genetics has revealed that mutagenesis of SRSF2 and SF3B1 drives myelodysplastic syndromes characterized by leukopenia, macrocytic anemia, myeloid, and erythroid dysplasia." (PMID 29875770, 2018). "Mutation of the spliceosome components SF3B1 and U2AF1 are recurrent driver events in many cancer types including chronic lymphoblastic leukemia, myelodysplastic syndrome, uveal melanoma and breast cancer." (PMID 28177281, 2017). "For example, genes that encode U2AF, SF3B1 and SRSF2 are mutated in myelodysplastic syndromes, while others promote cancer or provide a cancer-specific metabolic signature." (PMID 26529031, 2015). "Recurrent mutations in the highly conserved HEAT 5–9 repeats of splicing factor 3B subunit 1 (SF3B1) have been reported in myelodysplastic syndrome, chronic lymphocytic leukemia (CLL), breast cancer (BRCA), uveal melanoma (UM), and pancreatic cancer." (PMID 25768983, 2015). "By contrast, mutations affecting spliceosome genes SF3B1 and SRSF2, closely associated with the myelodysplastic syndromes, were identified only in those aged >70 years, with several individuals harboring more than one such mutation." (PMID 25732814, 2015). "SF3B1 mutations had been previously detected in myeloid malignancies such as CLL (chronic lymphoid leukemia) and MDS (myelodysplastic syndrome) and also reported in breast cancer." (PMID 23694694, 2013). "SF3B1 mutation is common in myelodysplastic syndrome and other blood disorders, but it is not clear how this confers an advantage on mutant cells." (PMID 40027643, 2025). "•This study identified four compounds, two of these FDA approved drugs, that target the mutational hot spot K700E and functional amino acid residue R630 that may have the potential to modulate SF3B1 activity in myelodysplastic syndrome (MDS) and other neoplasms linked to SF3B1 splicing control." (PMID 38975181, 2024). "Recently, SF3B1 mutations in uveal melanoma (UVM), myelodysplastic syndrome (MDS), and CLL were associated with mis-splicing of Bromodomain Containing 9 (BRD9), a subunit of the non-canonical BRG1 (SMARCA4) or BRM (SMARCA2) associated factor (ncBAF) chromatin remodeling complex." (PMID 39261602, 2024).
myelodysplastic syndrome (continued). "Significant sex differences exist in the genomic aberrations underlying disease pathology, including a higher prevalence of SF3B1, SRSF2, and ASXL1 mutations in males and DNMT3A mutations in females with clonal hematopoiesis indeterminate potential and myelodysplastic syndromes (MDS)." (PMID 39402216, 2024). "The authors investigated circular RNA (circRNA) processing in patients with myelodysplastic neoplasms and observed upregulation of circRNAs derived from the zinc finger E‐box binding homeobox 1 (ZEB1) gene exclusively in patients with mutated splicing factor 3b subunit 1 (SF3B1)." (PMID 37408496, 2023). "Recurrent, heterozygous and mutually exclusive mutations of splicing factors SF3B1, SRSF2 and U2AF1 frequently occur in blood and solid cancers (for instance in myelodysplastic syndromes, chronic lymphocytic leukaemia, acute myeloid leukaemia, uveal melanoma and breast cancer)." (PMID 36855776, 2023). "We investigated five patients with previous history of MPN, which four had initial diagnosis of ET (one case harboring JAK2 p.Val617Phe and the remaining three CALR type II p.Lys385fs*47), and one was diagnosed with MPN/myelodysplastic syndrome with thrombocytosis (SF3B1 p.Lys700Glu)." (PMID 29515972, 2018). "While the function of SF3B1 in cancer is not well established, its mutations are frequently observed in myelodysplastic syndromes." (PMID 27175787, 2016). "Mutations in spliceosomal genes, in particular splicing factor 3 subunit b1 (SF3b1), were first identified in myelodysplastic syndromes (MDS), myeloproliferative neoplasms (MPN), MDS/MPN, and chronic lymphocytic leukemia (CLL), as well as other hematological disorders." (PMID 25375204, 2014). "SF3B1 is altered in approximately 15–20% of all myelodysplastic syndromes (MDS) patients, and this alteration increases to over 80% in MDS, specifically with ring sideroblasts (RS)." (PMID 40729294, 2024). "Mutations in RNA splicing factor genes including SF3B1, U2AF1, SRSF2, and ZRSR2 have been reported to contribute to development of myeloid neoplasms including myelodysplastic syndrome (MDS) and secondary acute myeloid leukemia (sAML)." (PMID 38883705, 2024). "Mutated variants of SF3B1 (SF3B1MUT) are seen in hematological malignancies like CLL and myelodysplastic syndromes (MDS) but also in solid tumors such as uveal melanoma (UM), mucosal melanoma, BRCA, pancreatic, and prostate cancer." (PMID 38731892, 2024). "In this study, we focus on the relationship between SF3B1 and four types of cancer, namely myelodysplastic syndrome (MDS), acute myeloid leukemia (AML), and chronic lymphocytic leukemia (CLL) and breast cancer (BC)." (PMID 36792691, 2023). "Suggesting the regulation of SLC25A37 by the splicing factor SF3B1, a splice variant of SLC25A37 was detected in the bone marrow cells of patients with myelodysplastic syndrome (MDS) and a mutation SF3B1, the gene most often mutated in MDS." (PMID 36359860, 2022). "Recurrent somatic mutations of the SFG, such as SF3B1, SRSF2, U2AF1, and ZRSR2, have been uncovered in myelodysplastic syndrome (MDS), chronic lymphocytic leukemia, acute myeloid leukemia, breast cancer, lung adenocarcinoma, and uveal melanoma." (PMID 36684432, 2022). "In addition, altered expression of splicing factors, such as subunit 1 of splicing factor 3 (SF3B1), may also be involved in myelodysplastic syndrome and AML." (PMID 36230605, 2022). "Genes of the spliceosome-complex including SRSF2, SF3B1, U2AF1, and ZRSR2 are frequently mutated in myeloid malignancies such as AML, myelodysplastic syndromes (MDS) or myeloproliferative disorders." (PMID 33692956, 2021). "SF3B1 is the most frequently mutated component of a spliceosome associated with diseases such as chronic lymphocytic leukemia (CLL), chronic myelomonocytic leukemia (CMML), myelodysplastic syndrome (MDS), and breast and pancreatic cancers and is the best-known drug target in spliceosomes." (PMID 33317029, 2020).
myelodysplastic syndrome (continued). "Large-scale cancer genome sequencing projects have identified recurrent somatic mutations in SF3B1 in several types of hematological malignancies including chronic lymphocytic leukemia (CLL), acute myeloid leukemia (AML), and myelodysplastic syndromes (MDS)." (PMID 39303038, 2024). "Moreover, a colony assay targeting a patient with myelodysplastic syndrome (MDS)/MPN-RS-T harboring both JAK2 exon 12 (p.H538_K539delinsL) and SF3B1E622D mutations demonstrated that SF3B1-mutated clones existed in isolation but all clones with JAK2 exon 12 mutations had accompanying SF3B1 mutations." (PMID 37629188, 2023). "Interestingly, high SF3B1 levels correlated with higher usage of alternative 3′ splice sites, resembling common alterations in SF3B1-mutated cancers, and with elevated exon skipping, which has been linked to PDAC and to SF3B1-mutation in myelodysplastic syndromes and C. elegans models." (PMID 34857016, 2021). "Splicing of mRNA (e.g., in SF3B1, SRSF2) also occurred in haematological tumours such as myelodysplastic syndrome (MDS) and chronic lymphocytic leukaemia (CLL) resulting in resistance to treatment." (PMID 33670515, 2021). "Considering that the mutation is frequently seen in myelodysplastic syndrome (MDS), chronic lymphocytic leukemia (CLL) and breast cancer our results can be used to study other cancer types, and mutant SF3B1 can be considered a potential drug target for cancer therapy." (PMID 32354150, 2020). "Studies revealed that there are also mRNA splicing events, particularly in SF3B1, U2AF1, and SRSF2, in hematological tumors such as chronic lymphocytic leukemia (CLL) and myelodysplastic syndrome (MDS)." (PMID 31798590, 2019). "Mutations in LUC7L2, PRPF8,SF3B1, SRSF2, U2AF1, and ZRSR2 genes occur at various frequencies ranging between 40% and 85% in different subtypes of myelodysplastic syndrome (MDS) and 5% and 10% of acute myeloid leukemia (AML) and myeloproliferative neoplasms (MPNs)." (PMID 31766606, 2019). "This is unlike myelodysplastic syndrome with ring sideroblasts (MDS-RS), where only 5% bone marrow RS is required in the presence of SF3B1 mutation." (PMID 38714876, 2024). "For instance, SF3B1, a crucial constituent in the RNA splicing cascade, when mutated, disrupts normal splicing mechanisms, resulting in aberrant mRNA and protein synthesis, a phenomenon commonly observed in malignancies such as chronic lymphocytic leukemia (CLL) and myelodysplastic syndromes (MDS)." (PMID 40395612, 2024). "Myelodysplastic syndromes are shaped by gene aberrations involved in NF1 and SF3B1." (PMID 31466283, 2019). "For example, while SF3B1 mutation occurs at high frequency in myelodysplastic syndrome (MDS) and acute myeloid leukemia (AML), the only isogenic SF3B1 mutant myeloid cell line is in K-562, a chronic myelogenous leukemia (CML) cell line." (PMID 39194178, 2024). "We also ran this analysis in parallel for data from hematopoietic progenitors of patients with myelodysplastic syndrome (MDS), a disorder well-known for significant impairments in terminal erythropoiesis, either with or without somatic mutations in the related splicing factor SF3B1." (PMID 31070582, 2019).